PCED1B (PC-esterase domain containing 1B)
Synonyms: FAM113B; MGC16044
Tractability: No criterion of Open Targets' tractability assessment is met for any kind of drug.
Gene: Protein-coding gene on chromosome 12 (47,077,945 to 47,236,664, forward strand). Ensembl gene ENSG00000179715.
Subcellular location (Human Protein Atlas): Golgi apparatus; Vesicles
Gene Ontology:
Molecular function: protein binding
Genetic constraint (gnomAD): Loss-of-function variants: 1 observed, 0.43 expected, observed/expected ratio (o/e) 2.3. That is too few expected variants to judge how well the gene tolerates losing a copy. Missense variants: 573 observed, 586.96 expected, observed/expected ratio (o/e) 0.98, 90% interval 0.91 to 1.05. Synonymous variants: 251 observed, 251.27 expected, observed/expected ratio (o/e) 1, 90% interval 0.9 to 1.11.
Homologues: Orthologues: chimpanzee PCED1B (99% identical), macaque PCED1B (92% identical), pig PCED1B (62% identical), dog PCED1B (61% identical), rat Pced1b (59% identical), rabbit PCED1B (59% identical), mouse Pced1b (58% identical), zebrafish fam113 (35% identical), tropical clawed frog pced1a (34% identical), Caenorhabditis elegans D2030.8 (25% identical). Paralogues in human: PCED1A (53% identical).
Diseases named in the same sentence as PCED1B in open-access papers:
PCED1B is named in the same sentence as 12 diseases in open-access papers, as found by Europe PMC text mining. Sharing a sentence is not in itself a finding about the gene and the disease. The quoted sentences say what the papers report.
glioma (2 papers, 2021 to 2022). A benign or malignant brain and spinal cord tumor that arises from glial cells (astrocytes, oligodendrocytes, ependymal cells). "LncRNA acts as a ceRNA to target PCED1B mediated by miR-194-5p to promote glioma cell proliferation and inhibit cell apoptosis." (PMID 34324544, 2021). "PCED1B.AS1 has been reported to cooperate with Mir-194-5p to promote the proliferation of glioma and inhibit the apoptosis of glioma cells and promote glioblastoma genesis through upregulation of HIF-1alpha." (PMID 36033510, 2022).
tuberculosis (2 papers, 2023 to 2024). A chronic, recurrent infection caused by the bacterium Mycobacterium tuberculosis. "Lastly, we found that PCED1B is associated with tuberculosis, in line with another recent study." (PMID 37108169, 2023).
meningioma (1 paper, 2023). A generally slow growing tumor attached to the dura mater. "Investigation of antigen distribution across all WHO grades yielded six common meningioma-associated antigens (A4GALT, FBN2, SNED1, MPP6, PCED1B, and ANGEL2)." (PMID 37368072, 2023).
multiple myeloma (1 paper, 2021). "High expression of PAFAH1B3 and SIAE, and low expression of PCED1B were identified as poor prognostic markers in patients with multiple myeloma, suggesting a role for these esterases in myeloma biology." (PMID 33531688, 2021).
myeloma (1 paper, 2021). "High expression of OVCA2, PAFAH1B3, USP4 and SIAE, and low expression of PCED1B, are poor prognostic markers in MM, suggesting a role for these esterases in myeloma biology." (PMID 33531688, 2021).
infectious disease (1 paper, 2023). A disorder directly resulting from the presence and activity of a microbial, viral, or parasitic agent in humans. "Only three genes overlap between the three studies, with CACNA1E being overexpressed, whereas CD28 and PCED1B had lower expression levels in patients with infectious disease." (PMID 37108169, 2023).
respiratory disease (1 paper, 2024). "PCED1B was also previously associated with bovine respiratory disease susceptibility." (PMID 38892353, 2024).
PCED1B also shares sentences with these, for which no sentence is quoted: adenocarcinoma (1 paper); cancer (1); glioblastoma (1); hepatocellular carcinoma (1); tumor (1).